ENSG00000276784
Gene: Miscellaneous RNA gene on chromosome X (73,944,595 to 73,944,663, forward strand). Ensembl gene ENSG00000276784.
Gene Ontology:
Biological process: positive regulation of gene expression